IL6 (interleukin 6)
Diseases named in the same sentence as IL6 in open-access papers (continued):
Sharing a sentence is not in itself a finding about the gene and the disease.
metabolic syndrome (continued). "Sarcopenia and CVD share common inflammatory pathways, including elevated cytokine levels, such as IL-6 and TNF-α, which contribute to vascular dysfunction and metabolic syndrome." (PMID 40430117, 2025). "The patients had dyslipidemia, mild increases in HOMA-IR, circulating creatinine, inflammatory biomarkers (hs-CRP, TNF-alpha, IL-6), and indicators of fibrosis (galectin-3 and sST2)." (PMID 40299414, 2025). "In agreement with Abrass’s study, we also found that the TNF-α, SREBP-1c, PAI-1, IL-6, and TGF-β mRNA levels were significantly increased in diabetic hamsters with dyslipidemia." (PMID 41012372, 2025). "For instance, in metabolic syndrome (MetS) and type 2 diabetes (T2D), increased BChE levels correlate with markers such as leptin, glucose, cholesterol, inflammatory mediators like interleukin-6 (IL-6), and oxidative stress indicators such as superoxide anion." (PMID 40612057, 2025). "A relationship between certain cytokines (IL-6 and TNF-α) and E2 has been documented in male patients with metabolic syndrome." (PMID 40564184, 2025). "On the other hand, some egg studies have found that participants who were overweight or who had metabolic syndrome experienced a reduction in inflammatory markers after egg interventions (3 eggs/day for 4–12 weeks led to reductions in TNF-α, IL-6, and CRP)." (PMID 40647165, 2025). "Although IL-6 showed strong associations with selected components of metabolic syndrome, it was not significantly correlated with the overall risk of MetS in this study." (PMID 40137151, 2025). "A cohort of 600 KOA patients was analyzed, revealing significant correlations between dyslipidemia (low HDL, high LDL) and inflammatory biomarkers (CRP, IL-6)." (PMID 40078412, 2025). "Inflammation was present in metabolic syndrome rats, supported by high levels of serum TNF-α (96.88 ± 15.02 pg/mL) and IL-6 (21.38 ± 4.02 pg/mL) compared to control rats (TNF-α: 38.30 ± 8.25 pg/mL, 6.44 ± 1.50 pg/mL) (p < 0.05)." (PMID 40141836, 2025). "The toxicity is observed in the form of dyslipidemia, oxidative stress (increased MDA and NO and decreased GSH, SOD, CAT, and GST), and inflammatory responses (increased TNF-α and IL-6)." (PMID 40407528, 2025). "Also, the induction of IL-6 might be a major contributor that aggravates HCD-induced dyslipidemia." (PMID 39598346, 2024). "This reduces the production of pro-inflammatory cytokines such as interleukin-6 (IL-6) and tumor necrosis factor-alpha (TNF-α), thereby mitigating chronic inflammation, a central feature of metabolic syndrome." (PMID 39796335, 2024). "Within patients affected by metabolic syndrome, there is a heightened production of proinflammatory mediators, such as leptin, TNF-α, and IL-6, creating a mutually reinforcing cycle that exacerbates both conditions." (PMID 39767248, 2024). "The concentrations of early metabolic syndrome biomarkers [adiponectin, leptin, TNF-α, IL-1, IL-6, IL-10, endothelin-1, apolipoprotein B, and lipoprotein (a)] were measured and a cardiopulmonary exercise test (CPET) was performed." (PMID 38254811, 2024). "In particular, the MedDiet proved effective in reducing IL-6 and CRP in individuals with metabolic syndrome compared to controls." (PMID 38613111, 2024). "Supplementation with alpha-linolenic acid (ALA) on the other hand has also been analyzed with positive results in reducing inflammatory parameters, such as IL-6 (Interleukin-6), CRP (C-reactive protein), and fasting glucose, in subjects with dyslipidemia." (PMID 38605945, 2024). "In terms of dyslipidemia, B symptoms, molecular typing, BCL2 fusion translation, ferritin, CRP, and IL-6 have influenced dyslipidemia (p <0.05)." (PMID 37384286, 2023). "TNF-α and IL-6 are also related to non-alcoholic fatty liver disease (NAFLD), a hepatic repercussion of the Metabolic syndrome." (PMID 38027196, 2023).
metabolic syndrome (continued). "This leads to the metabolic syndrome and similar to leptin, in vitro studies have shown that ASF produces more IL-6 than VSF making the link between ASF and metabolic syndrome stronger than that for VSF." (PMID 36200436, 2023). "In human adipose tissue, BPA stimulates the release of cytokines favouring adiposity namely interleukin-6 (IL-6) and tumor necrosis factor alpha (TNF-α), whereas it inhibits the release of adiponectin that acts protective against metabolic syndrome." (PMID 36676087, 2023). "The association between hemoglobin levels and SSI in T2DM was also observed after additional adjustment for potential confounders: age, sex, HT, current smokers, dyslipidemia, ACR, BMI, phosphorus, TNFα, IL6, and hs-CRP." (PMID 37762433, 2023). "Pro-inflammatory cytokines, such as IL-1β, IL-6, and TNF-α, are produced in adipose tissues during pathogenesis of metabolic syndrome." (PMID 36826001, 2023). "Pro-inflammatory cytokines like leptin, IL-6 and TNF-α are noted to be formed in adipose tissues during pathogenesis of metabolic syndrome, and the anti-inflammatory cytokine, adiponectin has the power to counteract their harmful sequels." (PMID 36826001, 2023). "Those with metabolic syndrome were significantly older (p = 0.000), and levels of MDA (p = 0.003), homocysteine (p = 0.001), IL-6 (p = 0.017) and IL-4 (p = 0.000) were significantly higher among them." (PMID 37571341, 2023). "The modulation of cytokines such as IL-6 and TNF-α was observed in Bifidobacterium lactis HN019-treated patients with metabolic syndrome in addition to a decrease in weight gain." (PMID 36674680, 2023). "The correlation between Klotho and SSI was also observed even after additional adjustment for potential confounders: age, sex, HT, current smokers, dyslipidemia, ACR, body mass index (BMI), phosphorus, iFGF23, TNFα, IL6, and hs-CRP." (PMID 37686263, 2023). "Elevated levels of pro-inflammatory cytokines, such as IL-6, CRP, and tumor necrosis factor (TNF)-α, have been observed in both periodontal disease and dyslipidemia." (PMID 37711924, 2023). "Recent study on PAHs exposure in small population suggested elevation of inflammation (IL2, IL6, IL8) and oxidative stress marker (MDA) in prediabetic patients, indicating a metabolic syndrome enhanced oxidative damage." (PMID 35844632, 2022). "The diet-induced obese hamster model displayed not only the expected metabolic comorbidities (dyslipidemia and NASH/liver fibrosis) but also a pro-inflammatory profile (with elevated serum levels of IL-6 and MCP-1) in the steady state." (PMID 36146875, 2022). "Compared to the normal baseline, IL-6 level was significantly higher among the groups with high total cholesterol, LDL-C, TG, and dyslipidemia." (PMID 36032093, 2022). "ME alleviated dyslipidemia and lipid accumulation, as well as pro-inflammatory cytokine production such as tumor necrosis factor-α (TNF-α), interleukin 6 (IL-6), and monocyte chemoattractant protein 1 (MCP1) in the WAT." (PMID 34573085, 2021). "We reported recently that IL‐38 plasma concentrations correlate inversely with IL‐6 and CRP in overweight subjects, and are most reduced in subjects with metabolic syndrome." (PMID 33620105, 2021). "The main novelty of the study is that it provides the first evidence in adolescents for a connection between hepcidin levels and MetS dyslipidemia in a framework of increased VAI and IL-6." (PMID 34065056, 2021). "In a large population from the SardiNIA Study, the correlation between metabolic syndrome, aortic stiffness, and carotid IMT and a panel of adipokines including adiponectin, leptin, IL-6, and MCP-1 was investigated." (PMID 34202323, 2021). "A progressive increase in IL-6 was also found in steatosis and NASH patients, as well as in patients with metabolic syndrome." (PMID 32824349, 2020). "Consumption of a Mediterranean diet resulted in significantly lower IL-6 and CRP concentrations individuals with metabolic syndrome when compared to controls." (PMID 32878326, 2020).
metabolic syndrome (continued). "Inflammation markers (IL-6, TNF-a and CRP) correlate positively with weight, and the metabolic syndrome is related to pro-inflammation and coagulation." (PMID 33108241, 2020). "As part of the adaptive reaction to infection from the immune system, inflammation measured by levels of serum inflammatory markers, such as interleukin 6 (IL-6) and C-reactive protein (CRP), can trigger a set of metabolic syndromes and behavioral regulations." (PMID 32140686, 2020). "Here we report that the practice of moderate acute exercise (60–70% of HRmax) for 30 min by metabolic syndrome patients increased TNFα and ICAM1 concentrations but maintained pre-exercise concentrations of IL6 at 30 min post-exercise." (PMID 32646062, 2020). "The aim of this research was to investigate the effect of 6-week aerobic exercise with moderate intensity and consumption of nano-curcumin on IL-6, IL-10 and BDNF in 60–65 year females with metabolic syndrome (MS)." (PMID 32256716, 2020). "Inflammation markers (IL-6, TNF-a and CRP) correlate positively with weight, and metabolic syndrome is related to pro-inflammation and coagulation." (PMID 33108241, 2020). "We developed a new nomogram to predict the 5-year incidence of CVD based on age, interleukin-6 (IL-6), and adiponectin (APN) levels, diastolic blood pressure, and dyslipidemia." (PMID 31191115, 2019). "Various inflammation markers including NFκβ, TNFα, interleukin-6 (IL-6), monocyte chemoattractant protein (MCP-1), visfatin, resistin, leptin and adiponectin have been identified in the metabolic syndrome pathogenesis." (PMID 31462242, 2019). "Our data also showed that reperfusion injury following cerebral ischemia in metabolic syndrome rats increased TNF-α and IL-6 together with the cognitive impairment which were in agreement with the previous study." (PMID 30937145, 2019). "However, the inflammation and oxidative stress in metabolic syndrome is described as a chronic low-grade state, which may be the reason for the unchanged plasma catalase activities in H rats, and the undetectable plasma IL-6 concentrations." (PMID 30287733, 2018). "Significantly higher concentrations of leptin, chemerin, IL-6, and HOMA-IR and decreased adiponectin concentrations were observed in patients with the metabolic syndrome." (PMID 30627158, 2018). "In our study, we found that such variables such as BMI, waist circumference, WHR, TGs, HDL, leptin, adiponectin, chemerin, and IL-6 are related to HOMA-I, which in turn is related to metabolic syndrome." (PMID 30627158, 2018). "Third, we didn’t measure the plasma hs-CRP, IL-6 and TNF in this study,then we cannot analyze these indexes’ effects on the development of dyslipidemia, we would take those indexes into account in further research." (PMID 30447693, 2018). "Metabolic syndrome can transiently occur in lean individuals during infection, where increased secretion of TNF, IL-6 and IL-1 by macrophages induces a temporary insulin-resistant state." (PMID 29954107, 2018). "They reported the efficacy of P. oleracea to increase the cell viability and improve dyslipidemia with different degrees, through antiinflammmtory effect, hence it lowers the levels of TNF- α and IL-6 that adipose cell secretes." (PMID 28077129, 2017). "Age induced dyslipidemia is thought to be due to increased inflammation due to high levels of Tumor necrosis alpha (TNF- α) and interleukin-6 (IL-6) which interfere with lipid metabolism." (PMID 28761616, 2017). "By lowering the levels of IL-6, cholesterol,TG, LDL-C, dyslipidemia and inflammatorysymptoms of PCOS will be improved." (PMID 28868839, 2017). "Ferretin, hs-CRP, IL-6, TNF-α, and LDL have all been shown to be elevated in those with metabolic syndrome." (PMID 29099041, 2017). "The potential biological mechanisms that link psoriasis and metabolic syndrome are chronic Th1- and Th17-mediated inflammation with dysregulation of cytokines, including tumor necrosis factor α (TNF-α) and interleukin 6 (IL-6)." (PMID 28496169, 2017).
metabolic syndrome (continued). "Obesity and dyslipidemia induce abnormal growth of adipose tissue, contributing to the overproduction of inflammatory mediators [particularly TNF-α, IL-6, and interleukin-1 beta (IL-1β)] and activation of nuclear factor-kappa B (NF-κB)." (PMID 28725195, 2017). "Interestingly, this human study was performed in metabolic syndrome patients challenged with a high-fat meal after 12 weeks on a high-fat diet, and showed a postprandial increase in NF-κB activation (p65 expression), mRNA levels of some inflammatory cytokines, and plasma concentration of IL-6." (PMID 29075306, 2017). "Dyslipidemia (abnormal cholesterol levels in blood) and inflammation of the white adipose tissue, two lipid disorders in metabolic syndrome, have been correlated to inflammatory biomarkers such as cytokines TNF-α and IL-6 and the C-reactive protein." (PMID 27635405, 2016). "Multivariable linear regression estimating associations between pericardial fat and right ventricular structure and function after accounting for metabolic syndrome, markers of systemic inflammation (CRP & IL-6), and in left ventricular morphology (n = 3,988)." (PMID 27311062, 2016). "A systemic pro-inflammatory and pro-coagulating state, illustrated by elevated levels of inflammatory markers such as IL-1, IL-6, TNF, and CRP, was reported among individuals with metabolic syndrome." (PMID 26964045, 2016). "Although no one had previously reported hyperlipidemia being related to CU, it has been shown that there is an increased level of inflammatory markers such as IL-1, Il-6, and TNF-α in patients with CU and those with metabolic syndrome." (PMID 26964045, 2016). "Our results that showed that CRP levels were significantly influenced by HDL, triglycerides, and IL-6 levels support a potential relationship between CRP levels and the metabolic syndrome." (PMID 26366318, 2015). "In order to explore the possible mechanism of L-arabinose on metabolic syndrome, six target genes related to metabolism including TNF-α, leptin, IL-6, ACCα, CPT-1α, and CPT-1α were measured by real-time PCR in liver and adipose tissues." (PMID 26652604, 2015). "We found that dyslipidemia after adjusting for age and disease activity and elevations of CRP and IL6 were the main factors negatively related to telomere lengthening in CS, even after controlling for other clinical and metabolic confounders." (PMID 25799396, 2015). "A few studies have indicated relationships between elevated levels of inflammatory mediators, such as IL-6, TNF-α, and C-reactive protein levels, and metabolic syndrome." (PMID 25587268, 2014). "A range of doses of aspirin (100 to 300 mg/day) reduced the plasma levels of inflammatory biomarkers such as CRP, IL-6 and TNF-α in patients with cardiovascular metabolic syndrome." (PMID 23506529, 2013). "Most of the recent studies showed that there was a correlation between inflammatory mediators (IL-6, TNF-α) and components of metabolic syndrome (MS)." (PMID 23865042, 2013). "Patients with metabolic syndrome often present with higher levels of systemic inflammatory markers such as CRP, TNF-α, Fibrinogen and IL-6, and these markers are also increased in the blood of COPD patients." (PMID 22701684, 2012). "In a large cohort consisting of men and women with known coronary artery disease, IL-18 was the only independent predictor of cardiovascular mortality in a subgroup with the metabolic syndrome, even after adjustment for CRP, IL-6 and fibrinogen." (PMID 20331890, 2010). "Third, the absence of key clinical covariates, such as body mass index (BMI), metabolic syndrome components, and systemic inflammatory markers (e.g., CRP, IL-6), may have led to residual confounding." (PMID 40868344, 2025). "Then, a reduction in IL-6 and IL-1β, but not in TNF-α, was observed after 8 weeks of consuming 75 g/day of whole grain products among overweight/obese individuals at risk of metabolic syndrome." (PMID 40944222, 2025).
metabolic syndrome (continued). "A study involving an 8-week intervention with bilberries in overweight/obese individuals with metabolic syndrome did not observe differences in IL-6, IL-12, or adiponectin at the end of the study." (PMID 40944222, 2025). "A systematic review with meta-analysis showed that consuming flaxseed products significantly reduced inflammatory cytokine IL-6 (rather than TNF-α) in dyslipidemia patients." (PMID 40507062, 2025). "Additionally, in individuals with metabolic syndrome, 4 weeks of consuming anthocyanin-rich berries significantly down-regulated the expression of NF-κB-dependent genes, including TNF-α, IL-6, IL-1A, PCAM-1, and COX-2." (PMID 41156509, 2025). "Elevated levels of IL-1, IL-6, and TNF-α in LPP may impair TG clearance by inhibiting lipoprotein lipase activity and reducing apoprotein-E levels, thus contributing to dyslipidemia." (PMID 40568287, 2025). "In the MOD group, diabetic rats exhibited significantly elevated levels of TC, TG, HDL-C, and LDL-C in serum, along with increased levels of IL-6 and TNF-α in plasma, signifying the presence of dyslipidemia and a severe inflammatory response induced by the high-fat diet." (PMID 38708085, 2024). "Patients with and without a metabolic syndrome differ in age, eGFR, serum creatinine and cystatin C concentrations, and plasma interleukin 6 concentration." (PMID 39064306, 2024). "We included age, gender (0=male, 1=female), Smoker (0=NO, 1=Yes), Drinker (0=NO, 1=Yes), thyroid-related hormones, IL-6, IL-15, TNF-α, dyslipidemia (0=NO, 1=Yes), and hypertension (0=NO, 1=Yes) as covariates to control for the influence of other relevant factors on LVM." (PMID 38356960, 2024). "Although the relationship between inflammation and dyslipidemia is not fully understood, epidemiological data showed that dyslipidemia patients exhibit a proinflammatory state that is characterized by higher cytokine levels, including TNF-α and IL-6." (PMID 38004051, 2023). "IL-6, sCD40L, p-Selectin, PSGL-1, PAI-1, tPA, D-Dimer, TF, and Factor IX levels were elevated in the groups with LC, especially in the subgroup of patients with metabolic syndrome (MetS)." (PMID 38139298, 2023). "Similarly, EAT LEPR expression was lower in individuals with dyslipidemia, as was PVAT IL6 expression." (PMID 36157437, 2022). "Moreover, the hormone concentrations in the human inflammatory fluids interdepend on the concentrations of tumour necrosis factor α (TNFα), interleukin 6 (IL6), and C-reactive protein (CRP), which are the main metabolic syndrome-related factors." (PMID 35055130, 2022). "Many genes such as APOB, LPL, APOA1, LEP, CD36, IL-6, and APOE may play an important role in dyslipidemia." (PMID 36061816, 2022). "Furthermore, obvious amelioration in dyslipidemia (lower triglycerides, total cholesterol and higher HDL) and decreased inflammatory markers (TNF-α and IL6) levels have been noticed after administration of AD-MSCs treated with OXA." (PMID 35083338, 2022). "In human studies, subjects with metabolic syndrome receiving blueberry showed a significant decline in superoxide and total ROS together with a reduction of inflammatory markers and reduced gene expression of TNF-α, TLR4, and IL-6." (PMID 35898615, 2022). "There is evidence that patients with metabolic syndrome have lower irisin and higher circulating C-reactive protein (CRP) and IL-6; likewise, individuals with central obesity have lower irisin concentrations when compared to individuals without central obesity." (PMID 34822430, 2021). "A lot of inflammatory molecules, synthesized by adipose tissues such as: IL-1, TNF-α, IL-6, adiponectin, serum amyloid A (SAA), and macrophages, could play an important role in the development of dyslipidemia." (PMID 33584134, 2021).